EGFR (epidermal growth factor receptor)
Diseases named in the same sentence as EGFR in open-access papers (continued):
Sharing a sentence is not in itself a finding about the gene and the disease.
chordoma (continued). "Additionally, two currently FDA approved drugs, afatinib and palbociclib (EGFR and CDK4/6 inhibitors, respectively) demonstrated synergy in vitro (CI50 = 0.43) while AZD2014 and afatanib also showed synergy (CI50 = 0.41) against a chordoma cell in vitro." (PMID 32737414, 2020). "A variety of molecular targets may be relevant therapeutically in chordoma, including platelet-derived growth factor receptor (PDGFR), epidermal growth factor receptor (EGFR), vascular endothelial growth factor receptor (VEGFR), mammalian target of rapamycin (mTOR), and the INI1 gene." (PMID 32850452, 2020). "Furthermore, EGFR activation has also been reported, and an European multi-center trial is evaluating the efficacy of afatinib, an ERBB family (EGFR/ERBB1, HER2/ERBB2, ERBB3, and ERBB4) inhibitor, as first-line or later-line treatment in advanced chordoma (NCT03083678)." (PMID 34868903, 2021). "However, four patients with EGFR-negative chordoma experienced PD after receiving the same regimen." (PMID 30775316, 2019). "The EGFR inhibitor afatinib, which we included as a positive control because it down-regulates TBXT, was equally harmful to chordoma cells but, as expected, not to the TBXT-negative and EGFR-inactive U2OS cells." (PMID 40901948, 2025). "Although clinical studies using receptor tyrosine kinase inhibitors such as EGFR inhibitors, VEGF inhibitors, and PDGFR inhibitors show some positive effects, there is no approved targeted therapy for general use in chordomas." (PMID 38786326, 2024). "N-(3-ethynylphenyl)-6,7-difluoroquinazolin-4-amine displayed weaker activity against EGFR in A431 cells (IC50 = 12 μM), and no potency in the four additional patient-derived chordoma cell lines or WS1 control (IC50 = > 100 μM)." (PMID 35896603, 2022). "There were still exceptions, including 44 and lead compound 45, both showing potent EGFR inhibition (IC50 = < 100 nM) but no activity against U-CH1 (IC50 = > 100 μM), again highlighting the complexity of chordoma biology." (PMID 35896603, 2022). "The 6-trifluoromethyl 16, while showing limited EGFR activity (IC50 = > 20 μM), displayed moderate activity against all four patient-derived chordoma cell lines, but this appeared to be driven by non-specific toxicity (WS1, IC50 = 18 μM)." (PMID 35896603, 2022). "We observed that EGFR (fold change: 2.652), MET (fold change: 4.676), AKT3 (fold change: 3.703) and EGF (fold change: 11.094) which is a ligand of EGFR, were down regulated in chordomas without dural penetration." (PMID 32533822, 2020). "Most tumors were positive by immunohistochemistry for PDGFR-α (92%), PDGFR-β (85%), c-Kit (77%), c-Met (96%), pAKT (82%), mTOR (56%), HER2 (24%), and EGFR (26%), yet imatinib, an FDA-approved drug that inhibits PDGFR-α, PDGFR-β, and c-Kit, has shown little to no efficacy in chordoma in vivo models." (PMID 32737414, 2020).
bone metastasis (75 papers, 2010 to 2026). Transfer of a neoplasm from its primary site to bones. "In clinical settings, individuals with advanced LUAD and EGFR mutations who present with symptoms of brain or bone metastasis generally receive a treatment regimen involving radiotherapy combined with EGFR‐TKIs." (PMID 38659399, 2024). "According to a previous report, the reason for the poor prognosis associated with bone metastasis in patients with advanced EGFR‐positive NSCLC is the presence, at a high frequency (72.7%), of multiple (three or more) distant metastases in these patients." (PMID 39245880, 2024). "Subsequently, LUAD with EGFR mutations responds well to thoracic radiotherapy or radiotherapy for brain/bone metastasis." (PMID 38659399, 2024). "NSCLC patients with brain metastasis (p = 0.025), liver metastasis (p = 0.012), bone metastasis (p = 0.014) and EGFR mutations (p = 0.033) had shorter OS." (PMID 37208639, 2023). "Patients with brain metastasis (p = 0.025), liver metastasis (p = 0.012), bone metastasis (p = 0.014) and EGFR mutations (p = 0.033) who received combination therapy with PD-1 inhibitors and antiangiogenic drugs had shorter OS." (PMID 37208639, 2023). "Higher BMI, the presence of brain and bone metastasis, and uncommon EGFR mutations were found to be factors associated with poorer PFS in multivariate analysis." (PMID 37340370, 2023). "previously proposed machine learning models to predict the EGFR mutation based on the bone metastasis in lumbar and thoracic spine, respectively." (PMID 37143947, 2023). "A recent study has revealed the association between MRI features derived from bone metastasis and the EGFR mutation sites in exons." (PMID 37143947, 2023). "Univariate analysis revealed that younger age, the presence of brain and bone metastasis, uncommon EGFR mutations, and high PD-L1 expression (≥ 1%), were all associated with worse PFS." (PMID 37340370, 2023). "Our investigation provided novel evidence and clinical-based support for the use of denosumab in NSCLC patients with bone metastasis and EGFR mutation." (PMID 35884531, 2022). "This study provided novel evidence of the survival benefit of denosumab for EGFR-mutated NSCLC patients with bone metastasis." (PMID 35884531, 2022). "In the multivariate model, primary EGFR mutation type, treatment mode, and status of bone metastasis and brain metastasis demonstrated a significant association with OS." (PMID 36159795, 2022). "Our study provided novel evidence of the survival benefit of denosumab for EGFR-mutated NSCLC patients with bone metastasis." (PMID 35884531, 2022). "The results also imply that the initiation time of denosumab should be earlier to prevent the occurrence of SREs in EGFR-mutated NSCLC patients with bone metastasis." (PMID 35884531, 2022). "This study is the first report to investigate the radiological effect of bone metastasis in patients with NSCLC harboring EGFR-TKIs sensitizing mutation treated with gefitinib." (PMID 36581856, 2022). "Recent reports have revealed that MRI features of bone metastasis are also related to EGFR mutation status." (PMID 35964032, 2022). "Univariate analysis showed that OS was significantly correlated with age, ECOG PS, pathological type, EGFR-mutation subtype, brain metastasis, bone metastasis, surgical history, chemotherapy, and baseline anemia." (PMID 36253772, 2022). "Studies have reported that patients harboring EGFR mutations are susceptible to developing bone metastasis." (PMID 35884531, 2022). "The present study showed that denosumab treatment was significantly correlated with improved overall survival (OS) in EGFR-mutated NSCLC patients with bone metastasis." (PMID 35884531, 2022). "Patient P140, who also had NSCLC with bone metastasis, had been treated with several rounds of chemotherapy before being tested for EGFR mutations." (PMID 36011410, 2022).
bone metastasis (continued). "Studies have shown that patients carrying EGFR mutations have a higher incidence of distant metastasis and are prone to the development of bone metastasis." (PMID 35884531, 2022). "Our study confirmed the association between initial SREs and a worse outcome and provided novel evidence of the survival benefit of denosumab for EGFR-mutated NSCLC patients with bone metastasis." (PMID 35884531, 2022). "In summary, this study demonstrated an association between bone metastasis and poor survival outcomes in EGFR-mutated NSCLC patients with bone metastasis." (PMID 35884531, 2022). "OS was significantly correlated with primary EGFR mutation, treatment mode, status of liver metastasis, status of bone metastasis, objective response and disease control." (PMID 36159795, 2022). "Univariate Cox regression analyses identified factors significantly associated with poorer PFS included concordant EGFR mutation detected in liquid/tissue biopsy, lymph node involvement, brain metastasis, and bone metastasis." (PMID 31652678, 2019). "Similar to their findings, our current study found that the concordant EGFR testing results in liquid/tissue biopsy was associated with lymph node involvement, brain metastasis, and bone metastasis." (PMID 31652678, 2019). "Using univariate logistic regression analysis, we found a few predicting factors for concordant EGFR mutation test results in liquid/tissue biopsy, including lymph node involvement (N1–3), brain metastasis, and bone metastasis." (PMID 31652678, 2019). "A retrospective clinical study found that the incidence of bone metastasis was similar in NSCLC patients with EGFR mutations compared to EGFR wild type patients." (PMID 26624882, 2016). "Our findings also showed that bone metastasis was an independent predictor of poor prognosis for advanced NSCLC patients with EGFR mutations received EGFR-TKIs treatment." (PMID 26624882, 2016). "Pulmonary nodules (p = 0.01), vertebral (p = 0.03) and other bone metastasis (p = 0.04) were identified to be significantly associated with EGFR mutations." (PMID 23922984, 2013). "The EGFR mutation was a positive prognostic marker of post-bone metastasis survival: EGFR mutation (−) n = 67, median post-bone metastasis survival 11.5 months (95% CI: 6.0–15.2); EGFR mutation (+) n = 39, median post-bone metastasis survival 28.8 months (95% CI: 18.1–35.7) (p < 0.05)." (PMID 39851958, 2025). "Overall, statistically significant differences were observed in the distribution of age, AJCC T stage, bone metastasis, pathological type, EGFR mutation status, surgery, chemotherapy, radiotherapy, EGFR-TKI treatment, and ICIs treatment between the male and female groups (P < 0.05)." (PMID 41272627, 2025). "Furthermore, a retrospective study has revealed that individuals with Stage IV LUAD and EGFR mutations gain benefits from radiotherapy for brain or bone metastasis." (PMID 38659399, 2024). "High AJCC staging (OR 1.98; p < 0.05), the use of EGFR inhibitor (OR 6.14; p < 0.05), high T‐staging (OR 1.47; p < 0.05), and the presence of lymphovascular invasion (OR 4.92; p < 0.05) increase predicted risk of bone metastasis." (PMID 39556481, 2024). "Moreover, among the individuals receiving EGFR‐TKIs combined with thoracic radiotherapy or radiotherapy for bone metastasis, those harboring the 19‐Del mutation exhibited better OS than those harboring the 21‐L858R mutation." (PMID 38659399, 2024). "EGFR mutations are associated with an increased risk of bone metastasis and poor prognosis." (PMID 38791037, 2024). "EGFR mutations were found to be more common in multiple metastases compared to single metastasis (24/40 vs. 12/42, respectively, p = 0.004), and EGFR + tumors were also associated with more frequent pleural (24.1% vs. 37.5%) and bone metastasis (31.5% vs. 53.8%)." (PMID 38711158, 2024).
bone metastasis (continued). "After multivariate analysis, higher body mass index, the presence of brain metastasis, bone metastasis, and uncommon EGFR mutations were correlated with worse PFS, while the presence of brain metastasis and high lung tumor E-cadherin score was associated with worse OS." (PMID 37340370, 2023). "At univariate analysis, age < 65 years (p = .024), heavy smoking (p = .005), Osteolytic BM (p = .034), number of bone metastasis ≥3 (p = .032), EGFR‐L858R mutated (p = .018) and bisphosphonate times <6 (p = .046), were significantly associated with worse overall survival (OS)." (PMID 35614541, 2023). "Univariate and multivariate analyses found that ECOG PS, brain metastasis, bone metastasis, surgical history, chemotherapy, and baseline anemia were independent prognostic factors for OS in patients with stage IV EGFR-mutated NSCLC who received targeted therapy." (PMID 36253772, 2022). "In terms of disease progression, there was no statistical significance in age, sex, smoking history, ECOG-PS, pathological type, brain metastasis, liver metastasis, bone metastasis, lung metastasis, adrenal metastasis, clinical stage, line of treatment, EGFR mutation and PD-L1 TPS." (PMID 36569915, 2022). "However, the effect of denosumab on survival of epidermal growth factor receptor (EGFR)-mutated NSCLC patients with bone metastasis has been insufficiently investigated." (PMID 35884531, 2022). "In addition, our results showed that patients with detectable baseline EGFR-activating mutations are significantly associated with bone metastasis." (PMID 36232650, 2022). "Patients with EGFR-activating mutations detected in baseline plasma were associated with bone metastasis (p = 0.002) and had shorter progression-free survival (12.9 vs. 17.7 months, p = 0.02) and overall survival (24.0 vs. 39.4 months, p = 0.02) compared to those without." (PMID 36232650, 2022). "In the present study, we aimed to investigate whether denosumab affects the outcome of EGFR-mutated NSCLC patients with bone metastasis in a real-world cohort." (PMID 35884531, 2022). "Patients with EGFRhigh in their PC tissue (continuous or dichotomized values) showed an increased risk of developing bone metastasis when performing Cox regression analyses; a risk that reached 3.462-fold (CI = 1.404–1.016, p = 0.008) when EGFR expression was dichotomized." (PMID 33918389, 2021). "Although with not statistically significant, the T790M mutation was observed more frequently in female patients (55.3%), in groups of baseline plasma positive for EGFR mutations (63.6%), bone metastasis (60.0%), and baseline liver metastasis (60.0%) compared to others." (PMID 30661185, 2019). "In consistence with our previous findings, univariate logistic regression analysis showed the same predicting factors for concordant EGFR mutation test results in liquid/tissue biopsy, including lymph node involvement (N1–3), brain metastasis, and bone metastasis (Table A2)." (PMID 31652678, 2019). "Therefore, EGFR mutation NSCLC patients in the course of disease with bone metastasis are very common." (PMID 26624882, 2016). "Notably, individuals with the 19‐Del mutation who received EGFR‐TKIs combined with thoracic or bone metastasis radiotherapy exhibited greater benefits compared with those with the 21‐L858R mutation (mOS: 51.0 vs. 30.15 months, p = 0.0013; 34.7 vs. 25.15 months, p = 0.0056, respectively)." (PMID 38659399, 2024). "High AJCC staging (odds ratio 1.98; p < 0.001), the use of EGFR inhibitor (odds ratio 6.14; p < 0.001), high T‐staging (odds ratio 1.47; p < 0.001), and the presence of lymphovascular invasion (odds ratio 4.92; p < 0.001) increase predicted bone metastasis risk." (PMID 39556481, 2024). "The mOS of individuals with Stage IV LUAD who received EGFR‐TKIs combined with radiotherapy (brain metastasis, bone metastasis, or thoracic radiotherapy) was 30.7, 31.9, and 36.6 months, respectively." (PMID 38659399, 2024).
bone metastasis (continued). "Cox proportional hazards regression analysis of the OS of patients with EGFR‐mutant NSCLC with bone metastasis (BoM)." (PMID 38549499, 2024). "Research, including a retrospective examination of clinical data, shows that bone metastasis can independently predict reduced progression-free survival (PFS) in patients treated with EGFR-TKIs, including osimertinib." (PMID 39108772, 2024). "Bone metastasis and CNS metastasis were identified as predictors of a poor prognosis in patients with EGFR‐positive NSCLC with PR." (PMID 39245880, 2024). "No remarkable variations were observed in the OS of the patient groups based on factors such gender, age, smoking status, presence of brain metastasis, presence of bone metastasis, EGFR‐TKIs treatment line, and chemotherapy application (all p > 0.05)." (PMID 38659399, 2024). "In our cohort, higher BMI and the presence of brain and bone metastasis were independently associated with unfavorable PFS, while the common EGFR mutation was independently associated with better PFS." (PMID 37340370, 2023). "In our present study, NSCLC patients with brain metastasis and bone metastasis had shorter PFS and OS, and patients with liver metastasis and EGFR mutations had shorter OS." (PMID 37208639, 2023). "We reviewed patients who were diagnosed with EGFR-mutant NSCLC with bone metastasis and received osimertinib as a first-line treatment between February 2018 and October 2022." (PMID 37674153, 2023). "At univariate analysis, age < 65 years, heavy smokers, EGFR L858R mutant, number of bone metastasis ≥3, bisphosphonate times <6, and osteogenic BM were significantly associated with worse OS." (PMID 35614541, 2023). "Our study has similar results, with age ≤ 57 years and bone metastasis decreasing the probability for one-year PFS in advanced EGFR-positive NSCLC patients." (PMID 37140694, 2023). "Osimertinib provided significantly longer PFS in patients with brain or bone metastasis and exon 19 deletion than the other EGFR-TKIs." (PMID 35698083, 2022). "A prospective randomized study enrolling more patients would be necessary to establish the effect of EGFR-TKI treatment on bone metastasis conclusively." (PMID 36581856, 2022). "In metastatic EGFR-mutated NSCLC, bone metastasis was associated with a poorer OS (21.7 vs. 33.0 months; p < 0.001)." (PMID 35884531, 2022). "The differences of maximum standardized uptake value (SUVmax) in primary tumor (pSUVmax), regional lymph node (nSUVmax) and bone metastasis (bmSUVmax) between different EGFR status groups were compared, alongside with common clinicopathological features." (PMID 32742498, 2020). "All of the included patients received bone biopsy; subsequent pathological evaluation and EGFR analysis were performed by bone metastasis tissue." (PMID 32742498, 2020). "Smoking history (P = 0.043), non-adenocarcinoma (P = 0.013), high architectural grade of LUAD (P = 0.019), EGFR wild status (P = 0.002), bone metastasis (P = 0.040) and brain metastasis (P = 0.042) were marginally correlated with worse PRS." (PMID 32093621, 2020). "Previous EGFR TKI treatment was associated with a lower risk of ADRs, whereas ECOG PS 2–4, female gender, bone metastasis, and previous and concomitant gastrointestinal disorders were all associated with a significantly higher risk of grade ≥ 3 ADRs." (PMID 30953238, 2019). "In this study, four worse prognostic factors (pre-treatment EGFR plasma and bone metastasis, new lesion, and high cfDNA concentration) with one favorable factor (surgery) were identified as the best model for overall survival." (PMID 30661185, 2019). "In line with this statement, significant relief of bone pain was observed in patients with bone metastasis in a clinical trial of the EGFR tyrosine kinase inhibitor." (PMID 28915604, 2017). "Confavreux and colleagues had reported that the incidence rate of bone metastasis was higher in EGFR-positive patients, comparing to the average rate in all stage IV NSCLC patients." (PMID 29113396, 2017).